KCNA1 (potassium voltage-gated channel subfamily A member 1)
Diseases named in the same sentence as KCNA1 in open-access papers (continued):
Sharing a sentence is not in itself a finding about the gene and the disease.
epilepsy (continued). "Both loss-of-function and gain-of-function mutations in KCNA1 can cause epilepsy." (PMID 39434833, 2024). "The findings suggest that KCNA1 mutations may contribute to the development and progression of epilepsy." (PMID 39767775, 2024). "It has been suggested that the occurrence of epilepsy or seizures in people with KCNA1 mutations may depend on where the mutation is located within the KCNA1 gene." (PMID 37594756, 2024). "In a previous review of pathogenic and likely pathogenic KCNA1 mutations, we identified links between genotype and disease phenotype, particularly for mutations associated with epilepsy, which tend to cluster in regions critical for the function of the channel’s pore." (PMID 37240170, 2023). "Interestingly, mutations in KCNA1 are considered to be potential biomarkers for sudden unexpected death in epilepsy patients (SUDEP), thus further highlighting the prospective benefit of Kv1.1-targeted therapeutic approaches." (PMID 38003469, 2023). "Notably, 83% (5/6) of the KCNA1 variants associated with respiratory dysfunction occur in patients with epilepsy." (PMID 37240170, 2023). "A number of studies have shown that Kcna1 is implicated in epilepsy." (PMID 37047515, 2023). "As respiratory dysfunction is hypothesized to be a primary risk factor for susceptibility to the cardiorespiratory dysfunction in epilepsy, this could reveal a new role for KCNA1 channelopathies in the regulation of basal respiratory physiology." (PMID 36884287, 2023). "Furthermore, mutations in Kv1.1 channels have been associated with epilepsy, and Kcna1-deficient mice are considered to be a model of sudden unexpected death in epilepsy (SUDEP), while also showing progressive respiratory dysfunction." (PMID 36884287, 2023). "The descriptions of breathing dysfunction in patients with KCNA1 channelopathy raise concern that it could increase the risk of sudden unexpected death in epilepsy (SUDEP), the leading cause of epilepsy-related mortality." (PMID 37240170, 2023). "The discovery of new KCNA1 mutations has provided significant insights into KCNA1-related epilepsy." (PMID 37240170, 2023). "Out of the 17 new KCNA1 variants examined in this review, eight are linked to epilepsy or seizures." (PMID 37240170, 2023). "Deletion of Kcna1/Kv1.1 or Kcna2/Kv1.2 has been reported to cause epilepsy in rodents." (PMID 36668838, 2022). "Interestingly, EA1 patients carrying KCNA1 mutations show increased incidence of epilepsy and, in the last years, variants in KCNA1 have been associated with epilepsy phenotypes with or without ataxia." (PMID 35897654, 2022). "On the other hand, KCNA1 and -2 variants are clearly linked to various NDDs and epilepsies." (PMID 35457207, 2022). "A subset of individuals with KCNA1 mutations may have severe forms of epilepsy, where identification of episodic ataxic symptoms may prove more difficult, including a small number of children harboring KCNA1 mutations with epileptic encephalopathy." (PMID 33833732, 2021). "Interestingly, in double‐mutant mice carrying the epilepsy‐causing Kcna1–/– mutation in addition to another epileptogenic mutation in the P/Q‐type calcium channel gene Cacna1a (Cacna1atottering), epilepsy was mutually suppressed." (PMID 33484493, 2021). "Analyses of the 47 deleterious KCNA1 mutations that were identified revealed that epilepsy or seizure-related variants tend to cluster in the S1/S2 transmembrane domains and in the pore region of Kv1.1, whereas EA1-associated variants occur along the whole length of the protein." (PMID 32316562, 2020). "However, the principal risk factor for epilepsy and premature death in the patient was probably the co-occurrence of the KCNA1 mutation with the non-synonymous SNP in SCN1A." (PMID 32316562, 2020).
epilepsy (continued). "In contrast with EA1-associated mutations, which span the whole length of Kv1.1, KCNA1 mutations associated with epilepsy or a family record of seizures appear to preferentially localize in certain domains of the Kv1.1 protein, specifically in the S1/S2 helices and the pore domain." (PMID 32316562, 2020). "Mutational experiments show that the nucleotide changes underlying both epilepsy-associated (V408L) and non-epilepsy-associated (I407M and V408A) variants reduce editing of the KCNA1 mRNA transcript by disrupting the complementarity required for hairpin duplex formation." (PMID 32316562, 2020). "This review sheds light on a potential location bias for KCNA1 mutations underlying epilepsy which could help to explain why seizures are a common comorbidity in EA1 patients; however, several questions still need to be explored." (PMID 32316562, 2020). "In mice, an engineered deletion of the entire Kcna1 open reading frame to generate a null mutation (Kcna1–/–) resulted in a severe epilepsy phenotype, characterized by spontaneous tonic-clonic seizures that occurred several times daily and culminated in sudden death in about half of animals." (PMID 31250689, 2019). "KCNA1 mutations may also lead to a sudden, unexpected death in epilepsy (SUDEP)." (PMID 39434833, 2024). "The discovery of several new KCNA1 variants that cause respiratory dysfunction related to seizures and/or sleep is particularly relevant for SUDEP, suggesting that epilepsy patients with KCNA1 mutations may be at increased risk of SUDEP and should receive enhanced surveillance." (PMID 37240170, 2023). "Research employing CRISPRa that might control the expression of a gene for the treatment of epilepsy targets the gene Kcna1 (encoding Kv1.1) because upregulating that gene results in lower neuronal excitability, and seizures are a burst of uncontrolled electrical activity between brain cells." (PMID 36297359, 2022). "Given the beneficial epistatic interactions between these two ion channel mutations in the context of epilepsy, in this work a battery of behavioral tests was employed to investigate whether the Scn2a and Kcna1 mutations interact to modify genotype–phenotype relationships in the context of autism." (PMID 33484493, 2021). "Thus, the numerous ASD‐like neurobehavioral phenotypes in Kcna1 mutant mice suggest that Kv1.1 deficiency may represent a new model for understanding autism pathomechanisms, especially in the context of epilepsy." (PMID 33484493, 2021). "Epilepsy‐associated Kv1.1 voltage‐gated potassium channel subunits encoded by the Kcna1 gene have traditionally been considered absent in heart, but recent studies reveal they are expressed in cardiomyocytes where they could regulate intrinsic cardiac electrophysiology." (PMID 33427415, 2021). "It was found that a family history of epilepsy was influenced by KCNA1/rs2227910, KCNAB1/rs4679773, and KCNJ10/rs12122979 (p-values = 0.039, 0.011, 0.047)." (PMID 40142207, 2025). "Mutations in ion channel genes such as SCN5A, KCNA1, and KCNH2 can manifest in both epilepsy and cardiac arrhythmia, illustrating the potential for a shared genetic basis for epilepsy and cardiac diseases." (PMID 40079478, 2025). "First, we studied KCNA/Kv1, Kcna1, Kcna2, Kcna3, Kcna4, Kcna5, and Kcna6 because of their involvement in neuronal excitability, epilepsy, and other neurological disorders." (PMID 41155561, 2025). "Kcna1 encodes for KV1.1, a voltage-gated potassium channel, and is a monogenetic risk gene for epilepsy." (PMID 39606727, 2024). "Compared to Dravet syndrome, considerably less is known about how metabolism is affected in KCNA1 epilepsy." (PMID 37594756, 2024). "We review existing studies regarding metabolism in epilepsies caused by mutations in sodium (SCN1A) and potassium (KCNA1) channels." (PMID 37594756, 2024).
epilepsy (continued). "The extent to which brain metabolism is affected in people with Dravet syndrome, KCNA1 epilepsy and the models thereof still requires clarification." (PMID 37594756, 2024). "Kcna1a (kcna1a and kcna1b are the zebrafish paralogues of the human KCNA1) knockdown and knockout zebrafish larvae have also been used as models of epilepsy." (PMID 37594756, 2024). "Here, we provide an overview of studies investigating metabolic alterations in epilepsies caused by mutations in the SCN1A and KCNA1 genes, which are currently the most studied ion channel epilepsies in animal models." (PMID 37594756, 2024). "The effects of these dietary metabolic therapies in people with and animal models of Dravet syndrome and KCNA1 epilepsy are reviewed below." (PMID 37594756, 2024). "We identified four key potassium channel genes, KCNA1, KCNA2, KCNJ11, and KCNS1, that are associated with the pathogenesis of epilepsy." (PMID 37483435, 2023). "These genetic modifiers usually exhibit a reduction in seizures and/or the incidence of sudden unexpected death in epilepsy (SUDEP) in Kcna1 KO mice." (PMID 37240170, 2023). "Among the new epilepsy-linked variants are several firsts, such as the first two gain-of-function (GOF) mutations ever discovered for KCNA1 and the first frameshift mutation." (PMID 37240170, 2023). "Recently described mutations in the Kv1.1 pore domain (G376S, G396R, and G396V) provide evidence for the possibility of genetic modifiers altering the clinical presentations of KCNA1 channelopathy, especially with regard to epilepsy phenotypes." (PMID 37240170, 2023). "As a result of the use of a mouse epilepsy model, KCNA1 knockout mice exhibited seizures, arrhythmia, increased vagal tone, and premature death, which was later validated in a human SUDEP case." (PMID 37181558, 2023). "Historically, three diseases have been predominantly associated with KCNA1 mutations, namely episodic ataxia type 1 (EA1), myokymia, and epilepsy." (PMID 37240170, 2023). "Scn8a and Slc7a11 are the two most recently identified genes that can modify aspects of epilepsy in Kcna1 KO mice." (PMID 37240170, 2023). "The aim of this study was to functionally characterize Kv1.1 mutant channel to provide a genotype–phenotype correlation and discuss therapeutic options for KCNA1-related epilepsy." (PMID 35897654, 2022). "Genetic variants in both KCNA1 and KCNA2, which disrupt the proline residues of the PVP motif, have been identified in children with severe epilepsy and comorbidities (P403S and P405S/L in Kv1.1 and P405L and P407A in Kv1.2)." (PMID 35897654, 2022). "Accordingly, individual #2 suffered also from epilepsy and myokymia, representing the diverse phenotypic spectrum of KCNA1-related disorders." (PMID 34305802, 2021). "In humans, KCNA1 mutations cause the movement disorder episodic ataxia type 1 (EA1), as well as epilepsy, which is characterized by spontaneous recurrent seizures." (PMID 33427415, 2021). "Previous studies have shown that Scn2a+/– ameliorates epilepsy in Kcna1–/– mice, improving survival, seizure characteristics, and brain–heart dynamics." (PMID 33484493, 2021). "The voltage-gated K+ channel gene KCNA1 (KV1.1) is also closely related to epilepsy, as confirmed by animal experiments." (PMID 33718116, 2020). "We complemented the chronic epilepsy study by looking at the effect of Kcna1-dCas9A treatment on acute seizures evoked by a different mechanism, focal pilocarpine injection in the visual cortex before and after doxycycline administration." (PMID 32129831, 2020). "Based on these findings, the repurposing of riluzole (a sodium channel and NMDA receptor blocker and BK channel activator), is suggested as a treatment for epilepsy caused by LGI1, KCNA1 or KCNA2 mutations." (PMID 32331416, 2020). "Not only do MC4R-specific agonists improve memory but ACTH-treatment in epileptic KCNA1-null mice demonstrated protection against learning and memory deficits induced by epilepsy." (PMID 32670020, 2020).
epilepsy (continued). "Lentivirus- or AAV-mediated overexpression of Kcna1 reduces neuronal excitability and, when targeted to principal cells, suppresses seizures in rodent models of epilepsy." (PMID 32129831, 2020). "Another model, the Kcna1-null mouse, has provided substantial insight into the importance of Kv1.1 in epilepsy, sleep, and cardiorespiratory function." (PMID 32316562, 2020). "Recently, neuron-specific Kcna1 conditional knockout (cKO) mice were developed to more precisely understand the role of Kcna1 in epilepsy and sudden death." (PMID 32316562, 2020). "While all Kcna1-null mice exhibit epilepsy and sleep deficits, they can also manifest differences in mortality and respiratory deficits depending on the genetic background of the mouse strain." (PMID 32316562, 2020). "A KD has also been shown to reduce spontaneous seizures and extend the lifespan of Kcna1-null mice, a model of early onset epilepsy and SUDEP." (PMID 30984098, 2019). "This study aims to investigate the effects of the three potassium channel genes KCNA1, KCNA2, and KCNV2 on increased susceptibility to epilepsy as well as on responsiveness to antiepileptic drugs (AEDs)." (PMID 30441785, 2018). "In this study, blood samples were collected from 299 healthy controls and 296 Jordanian Arab patients with epilepsy (consisting of 162 patients with good response and 134 patients with poor response), and seven KCNA1, KCNA2, and KCNV2 SNPs." (PMID 30441785, 2018). "In a Kcna1 knockout mouse model, genetic deletion of Sxc decreased aberrant neurogenesis in the dentate gyrus, preventing hippocampal enlargement despite persistent severe epilepsy." (PMID 40867142, 2025). "The ketogenic diet (KD) has demonstrated efficacy in improving epilepsy, enhancing the presence of intestinal Akkermansia muciniphila and Parabacteroides in two mouse seizure models: Kcna1−/− mouse (for generalized tonic-clonic seizures) and the 6 Hz- induced mouse acute seizure model." (PMID 40237060, 2025). "Additionally, the RNA-Seq analysis of hippocampi showed that Kcna1-dCas9A was able to rescue transcriptomic changes in this epilepsy model as well." (PMID 39937026, 2025). "When Kcna1−/− mice were transplanted with the GM from mice on KD, or specifically with Akkermansia and Parabacteroides, it was observed that both interventions attenuated epilepsy." (PMID 40237060, 2025). "KCNA1 influenced the history of febrile seizures and the history of epilepsy." (PMID 40142207, 2025). "The high mortality in Kcna1‐null mice appears to coincide with a decline in cardiorespiratory function, making it an ideal model to study sudden unexplained death in epilepsy (SUDEP)." (PMID 37594756, 2024). "Moreover, KCNA1 mutations can lead to abnormal Kv1.1 function, primarily associated with Episodic Ataxia Type 1 (EA1) and epilepsy." (PMID 38172959, 2024). "KCNA1 (Kv1.1) and KCNA2 (Kv1.2) have been associated with epilepsy." (PMID 39253727, 2024). "The role of KCNA1 in epilepsy has been studied using mouse models." (PMID 39767775, 2024). "This review summarises metabolic changes that have been found in people with epilepsy and in rodent seizure and epilepsy models, what is currently known about metabolism in specific epilepsies associated with mutations in SCN1A and KCNA1, and alterations found after ketogenic diet treatment." (PMID 37594756, 2024). "Of the newly discovered KCNA1 variants, nine of the mutations are not related to epilepsy but are instead linked with other diseases such as EA1, myokymia, musculoskeletal abnormalities, and nystagmus." (PMID 37240170, 2023). "Additionally, recent findings in mouse models have added to the growing list of genes that can modify Kcna1-related epilepsy." (PMID 37240170, 2023). "Loss-of-function mutations in the KCNA1(Kv1.1) gene cause episodic ataxia type 1 (EA1), a neurological disease characterized by cerebellar dysfunction, ataxic attacks, persistent myokymia with painful cramps in skeletal muscles, and epilepsy." (PMID 37487086, 2023).
epilepsy (continued). "Mutations in the KCNA1 gene can cause several neurological diseases and symptoms, such as episodic ataxia type 1 (EA1) and epilepsy, which may occur alone or in combination, making it challenging to establish simple genotype–phenotype correlations." (PMID 37240170, 2023). "Other KCNA1 variants occur without EA, and instead present with epilepsy, epileptic encephalopathy, hypomagnesemia, muscle cramps, myokymia, cataplexy, dystonia or paroxysmal kinesogenic dyskinesia." (PMID 37008993, 2023). "Moreover, they demonstrated how important the Kcna1 gene is in the epilepsy context and highlighted that it is a good target for further investigation." (PMID 34486831, 2022). "These cells share neuronal genes expressed in central excitatory neurons such as Kcna1, Kcnq2, Kcnq3, Scn1a, Scn8a, genes that are relevant to epilepsy." (PMID 36192157, 2022). "Additionally, reduced editing reported in the KCNA1 transcript in epilepsy was inversely correlated with disease duration." (PMID 35327657, 2022). "Using Kcna1 null mice (Kcna1−/−), a well-known mouse model of temporal lobe epilepsy, here we show that deletion of Kv1.1 subunits alters intrinsic excitability and synaptic activity in neurons from two amygdalar subdivisions known to be involved in epilepsy and epilepsy-related comorbidities." (PMID 34312446, 2021). "Pathogenic KCNA1 variants have been reported in patients with EA1 characterized by constant myokymia, episodic ataxia, and occasional epilepsy but normal cognition, and were unexpected in patients with severe epilepsy and significant cognitive impairment." (PMID 32705822, 2020). "Interestingly, Kcna2-null mice, which lack Kv1.2 subunits, also exhibit epilepsy and premature death phenotypes, but they appear more severely than in Kcna1-null mice." (PMID 32316562, 2020). "The link between KCNA1 and epilepsy was first discovered in mice and then in humans." (PMID 32331416, 2020). "Kcna1-null mutant mice model occupied with several characteristics, such as early onset epilepsy with a severe seizure phenotype with myoclonic and generalized tonic–clonic seizures, resistant to traditional AEDs, cognitively impaired, cardiac arrhythmias and sudden death." (PMID 30863356, 2019). "The lethal seizures associated with the absence of Kv1.1 has led to Kcna1–/– mice being widely used as a model for elucidating the mechanisms underlying sudden unexpected death in epilepsy (SUDEP)." (PMID 31250689, 2019). "Several point mutations of the KCNA1 gene coding for the Kv1.1 subunit, have been reported in patients suffering from episodic ataxia type 1 (EA1), an autosomal dominant neurological disease with paroxysmal cerebellar ataxia, epilepsy, myokymia." (PMID 29760657, 2018). "Moreover, our findings imply that the potassium voltage-gated channel subfamily A member 1 (Kcna1) may be involved in the modulation of DAPK1 in epilepsy." (PMID 37047515, 2023). "Therefore, LINC02242-hsa-let-7e-5p-KCNJ11 and LINC01963-hsa-miR-204-5p-KCNA1 might be involved in the regulation of epilepsy and brain injury." (PMID 37483435, 2023). "Therefore, it is not surprising that epilepsy has also been described to be a phenotypic feature of the known PxD-related KCNA1 variants p.Leu319Arg and p.Asn255Lys." (PMID 34305802, 2021). "Thus, the KCNA1 CNV is likely a key contributor to both the EE and SUDEP phenotypes, especially given the strong association between missense mutations in the PVP motif and severe forms of epilepsy and intellectual disability." (PMID 32316562, 2020). "Previously reported individuals with EA1 and epilepsy have shown to harbor dominant‐negative KCNA1 variants, suggesting that epilepsy might be related to a more severe disturbance of K1 channel function." (PMID 32705822, 2020). "In summary, our findings implicate excitatory forebrain neurons, with a possible influence of vagal afferents, as primary drivers of epilepsy and subsequent SUDEP in the Kcna1 mouse model." (PMID 39822954, 2025).